NGLY1 (N-glycanase 1)
Diseases named in the same sentence as NGLY1 in open-access papers (continued):
Sharing a sentence is not in itself a finding about the gene and the disease.
melanoma (continued). "Unlike NGLY1-knockdown melanoma cells, NGLY1-deficient COs showed undetectable GADD153 protein." (PMID 35322011, 2022). "Importantly, in vitro and in vivo experiments indicated that genetic and pharmacological inhibition of NGLY1 in melanoma cells exerts a strong anti-tumor effect, promotes apoptosis, and renders melanoma cells more sensitive to other chemotherapeutic agents, including bortezomib." (PMID 35406718, 2022). "Our results strongly support that NGLY1 suppression in melanoma cells elicits multifaceted cancer-elimination responses, and that targeting NGLY1 and protein deglycosylation may represent a novel anticancer strategy with the opportunity for a broad therapeutic window." (PMID 30385822, 2018). "While NGLY1 malfunction appeared to upregulate ATF4 in WA09 COs, this upregulation was moderate, compared with that in NGLY1-knockdown melanoma cells." (PMID 35322011, 2022). "Moreover, GAPDHS was identified as one of the top differentially expressed genes in human melanoma cells with NGLY1 knockdown, so it is also important to determine whether SOX10 cooperates with NGLY1 or other transcriptional regulators to promote melanomagenesis." (PMID 34249897, 2021). "Unlike normal cells, melanoma cells presented distinct responses and high vulnerability to NGLY1 suppression." (PMID 30385822, 2018). "Although ATF4 and GADD153 were upregulated in NGLY1-knockdown melanoma cells, we did not observe a clear upregulation of ER chaperones GRP78/94." (PMID 30385822, 2018). "The NGLY1 knockdown-induced upregulation of ATF4 and GADD153 was detected in melanoma cells." (PMID 30385822, 2018). "Unlike melanoma cells, human normal fibroblasts showed no significant changes in the production and release of IFNβ and IL-29 in response to NGLY1 knockdown." (PMID 30385822, 2018). "Using flow cytometry analysis, a substantial increase of apoptosis was detected in NGLY1-knockdown melanoma cells, which was absent in the cancer cells expressing NT-shRNA and normal cells expressing NGLY1-targeting shRNA." (PMID 30385822, 2018). "Additionally, NGLY1 inactivation triggers stress response-mediated cell death and upregulation of anticancer interferons in human melanoma cells but not normal dermal fibroblasts." (PMID 35322011, 2022). "Unlike melanoma cells, CO cells showed limited upregulation of ATF4 and GADD153 in response to NGLY1 loss, suggesting that NGLY1 dysfunction may cause distinct types or levels of stress in different cells." (PMID 35322011, 2022). "The missing of GRP78/94 upregulation suggests that the NGLY1 suppression-induced activation of ATF4 and GADD153 in melanoma cells may not be directly caused by ER stress." (PMID 30385822, 2018).
congenital disorder of deglycosylation (6 papers, 2019 to 2025). "Mutations in the NGLY1 gene in humans have been associated with a rare early-onset inherited disorder known as NGLY1 deficiency (also referred to as NGLY1-related congenital disorder of deglycosylation, NGLY1-CDDG, OMIM#615273)." (PMID 40644312, 2025). "Pathogenic variants in the NGLY1 gene are associated with a Congenital Disorder of Deglycosylation (CDDG) characterized by delays in reaching developmental milestones, complex hyperkinetic movement disorder, transient elevation of transaminases, and alacrima or hypolacrima." (PMID 32395402, 2020). "NGLY1 deficiency, also known as NGLY1-related congenital disorder of deglycosylation, is a rare autosomal recessive disorder caused by mutations in the NGLY1 gene which encodes a specialized enzyme called N-glycanase that removes N-linked glycan from glycosylated proteins within the body." (PMID 31326749, 2019). "Since the disorder was caused by pathologic mutations in the specific enzyme responsible for deglycosylation, the disease was named congenital disorder of deglycosylation (CDDG) or NGLY1-congenital disorder of deglycosylation (NGLY1-CDDG; OMIM#615273)." (PMID 35565658, 2022).
neuropathy (6 papers, 2019 to 2023). A disorder affecting the nervous system that manifests with pain, tingling, numbness, and/or muscle weakness. "The diminished pain sensation was reported in patients NGLY1 deficiency along with severe neuropathy." (PMID 36875753, 2023). "NGLY1 (N-glycanase 1) deficiency is related to neuropathy and the disorder of metabolism of protein, especially the dysfunction of endoplasmic reticulum." (PMID 35341155, 2022). "N-glycanase 1 (NGLY1) deficiency is a rare congenital disorder leading to global developmental delay and a multisystem syndrome including neuropathy." (PMID 34688664, 2021). "Together, these reports establish neuropathy as a major phenotype in NGLY1-deficient patients." (PMID 35406718, 2022). "Of note, previous work in C. elegans demonstrated a role for NGLY1 in axonal branching, suggesting a potential mechanism for the neuropathy observed in human patients." (PMID 35406718, 2022).
microcephaly (4 papers, 2020 to 2024). A congenital or acquired developmental disorder in which the circumference of the head is smaller than normal for the person's age and sex. "Patients with NGLY1 deficiency often present with global developmental delay accompanied by neurological symptoms, including microcephaly." (PMID 35322011, 2022). "The brain weights of Ngly1−/− rats were significantly lower than those of WT rats at 5, 15 and 29 weeks of age, implying microcephaly in Ngly1−/− rats, as observed with NGLY1-deficient patients." (PMID 32259258, 2020). "Because IGFBP2 and ID4 maintain NSCs as well as regulate cerebral and cognitive development, IGFBP2 and ID4 dysregulation during NGLY1-defective cortical development could limit proliferation and cause premature differentiation in NSCs, which may underlie microcephaly in NGLY1-deficiency patients." (PMID 35322011, 2022). "Mutations in N-glycanase 1 (NGLY1), which deglycosylates misfolded glycoproteins for degradation, can cause NGLY1 deficiency in patients and their abnormal fetal development in multiple organs, including microcephaly and other neurological disorders." (PMID 35322011, 2022).
Adrenal insufficiency (3 papers, 2019 to 2022). Insufficient production of steroid hormones (primarily cortisol) by the adrenal glands. "This was the first clue for a potential adrenal insufficiency in patients with NGLY1 deficiency." (PMID 35406718, 2022). "This case report, along with previous reports on significant vacuolization of adrenal cortex in other NGLY1 deficiency patients, suggests that a causal link might exist between NGLY1 mutation and adrenal insufficiency." (PMID 30740912, 2019). "We postulate that patients with NGLY1 mutations may develop adrenal insufficiency as a result of proteotoxic stress‐induced cell death, which could be an explanation for this increased mortality." (PMID 30740912, 2019). "We propose a causal link between NGLY1 mutation and adrenal insufficiency." (PMID 30740912, 2019). "We have described a girl with a homozygous NGLY1 mutation and proven adrenal insufficiency." (PMID 30740912, 2019). "We postulate that patients with NGLY1 deficiency may develop adrenal insufficiency as a consequence of impaired proteostasis, and the accompanying proteotoxic stress‐induced cell death, through defective Nrf1 function." (PMID 30740912, 2019). "At this point, we cannot exclude that the adrenal insufficiency observed in our patient was an incidental event not related to NGLY1 deficiency." (PMID 30740912, 2019).
liver disease (3 papers, 2022 to 2025). "In humans, pathogenic genetic variants in NGLY1 are linked to a variable phenotype of global neurological dysfunction, abnormal tear production, and liver disease presenting the rare autosomal recessive disorder N-glycanase deficiency." (PMID 35769264, 2022). "However, further characterization of the liver at the cellular level is essential and might explore additional molecular pathways involved in NGLY1‐CDDG liver disease." (PMID 40470739, 2025).
liver dysfunction (3 papers, 2022 to 2024). "Liver dysfunction was reported in the first-described patient with NGLY1 deficiency." (PMID 35406718, 2022).
scoliosis (3 papers, 2020 to 2024). A congenital or acquired spinal deformity characterized by lateral curvature of the spine. "Together, these results demonstrated that the iNgly1 mouse model recapitulated the key clinical features of NGLY1 deficiency in human patients, such as motor impairment and scoliosis." (PMID 39137042, 2024). "Scoliosis, which is one of the characteristics of NGLY1 deficiency subjects, was also observed in older Ngly1−/− rats at 29 weeks of age, but not at 5 and 15 weeks of age, although the penetrance was not high, and there was a sex difference in the penetrance (male, 6/10 rats; female, 2/10 rats)." (PMID 32259258, 2020). "As with human NGLY1 deficiency, all Ngly1−/− rats showed a motor deficit, whereas only some Ngly1−/− rats had scoliosis." (PMID 32259258, 2020).
Seizure (3 papers, 2022 to 2024). A seizure is an intermittent abnormality of nervous system physiology characterized by a transient occurrence of signs and/or symptoms due to abnormal excessive or synchronous neuronal activity in the brain. "Epileptic seizure is one of the symptoms in patients with NGLY1 deficiency, a congenital disorder of deglycosylation." (PMID 38649481, 2024). "Although epileptic seizure is one of the most severe symptoms in patients with NGLY1 deficiency, preclinical studies have not been conducted due to the lack of animal models for epileptic seizures in NGLY1 deficiency." (PMID 38649481, 2024). "Although epileptic seizure is one of the most severe symptoms in patients with NGLY1 deficiency, preclinical studies have not been carried out due to the lack of animal models for epileptic seizures in NGLY1 deficiency." (PMID 38649481, 2024).
ventricular septal defect (3 papers, 2017 to 2022). The presence of a defect (opening) in the septum that separates the two ventricles of the heart. "A loss-of-function mutation in the mouse Ngly1 (Ngly1tm1.1Tasuz) results in late embryonic lethality accompanied by ventricular septal defects (VSD)." (PMID 32720893, 2020). "In 2021, Dabaj and colleagues reported a patient with the classic findings of NGLY1 deficiency, along with CVI and a ventricular septal defect (VSD)." (PMID 35406718, 2022). "The Ngly1−/− embryos showed a ventricular septal defect (VSD) (5 out of 5 embryos (5/5))." (PMID 28426790, 2017).
acute lymphoblastic leukemia (2 papers, 2020 to 2023). Leukemia with an acute onset, characterized by the presence of lymphoblasts in the bone marrow and the peripheral blood. "Recently, researchers found that inhibition of VCP/p97 or NGLY1 by small molecules potentiates the cytotoxic effect of carfilzomib in MM and the T cell-derived acute lymphoblastic leukemia." (PMID 32344880, 2020).
amyotrophic lateral sclerosis (2 papers, 2021 to 2023). Amyotrophic lateral sclerosis (ALS) is a neurodegenerative disease characterized by progressive muscular paralysis reflecting degeneration of motor neurons in the primary motor cortex, corticospinal tracts, brainstem and spinal cord. "Studies within the last 5 yr have associated STING signaling with a wide range of neurodegenerative diseases including amyotrophic lateral sclerosis (ALS), frontotemporal dementia (FTD), PD, as well as several monogenic diseases such as NGLY1 deficiency and NPC disease." (PMID 36705629, 2023).
atypical Rett syndrome (2 papers, 2019 to 2022). A neurodevelopmental disorder that is diagnosed when a child presents with a Rett-like syndrome but does not fulfill all the diagnostic criteria for typical Rett syndrome (classic/typical RTT). "The musculoskeletal disorders documented here in NGLY1 deficiency are similar to those seen in other upper motor neuron disorders such as cerebral palsy (CP), but the clinical course of motor skills regression parallels other neurodegenerative disorders, such as Rett syndrome." (PMID 31217022, 2019).
Chronic constipation (2 papers, 2017 to 2018). Constipation for longer than three months with fewer than 3 bowel movements per week, straining, lumpy or hard stools, and a sensation of anorectal obstruction or incomplete defecation. "Finally, understanding the mechanisms underlying the food accumulation phenotype in Pngl–/– larvae might shed light on the pathophysiology of chronic constipation in NGLY1 deficiency patients." (PMID 28826503, 2017).
chronic myelogenous leukemia (2 papers, 2020). "We used K562 chronic myeloid leukemia cells to study NGLY1 deficiency because these cells are easy to handle, simple to manipulate, and express endogenous NGLY1 at a relatively high level." (PMID 32265286, 2020).
Failure to thrive (2 papers, 2022 to 2024). Failure to thrive (FTT) refers to a child whose physical growth is substantially below the norm. "The low Z-scores in height and weight suggest that failure to thrive is an important characteristic of this disease and that growth should be carefully monitored in patients with NGLY1 Deficiency." (PMID 36528660, 2022).
glycosylation disorder (2 papers, 2019). "As expected, this mutant had reduced PMM-2 enzymatic activity; by contrast, PMM-2 enzymatic activity was unchanged in a png-1 homozygous null mutant and model of NGLY1 deficiency (another glycosylation disorder) and in wild-type N2 worms." (PMID 31636082, 2019). "N-glycanase 1 (NGLY1) deficiency is an ultra-rare and complex monogenic glycosylation disorder that affects fewer than 40 patients globally." (PMID 31615832, 2019).
hepatocellular carcinoma (2 papers, 2019 to 2025). A malignant tumor that arises from hepatocytes. "In this study, we investigated the consequences of the loss of NGLY1 on ferroptosis and iron homeostasis using human hepatocellular carcinoma cells, HepG2." (PMID 40811347, 2025). "To investigate the consequences of loss of NGLY1 on cellular homeostasis and lipid metabolism, we generated NGLY1-KO HepG2 (human hepatocellular carcinoma cells) cell lines." (PMID 40811347, 2025).
acute myeloid leukemia (1 paper, 2020). Acute myeloid leukemia (AML) is a group of neoplasms arising from precursor cells committed to the myeloid cell-line differentiation. "Indeed, Nrf1, DDI2, and NGLY1 exhibit a correlated essentiality for cell survival in several acute myeloid leukemia (AML) cell lines." (PMID 32456207, 2020).
Cerebral visual impairment (1 paper, 2020). A form of loss of vision caused by damage to the visual cortex rather than a defect in the eye. "NGLY1 is related to cerebral visual impairment (CVI) in humans." (PMID 32143300, 2020).
Cirrhosis (1 paper, 2021). A chronic disorder of the liver in which liver tissue becomes scarred and is partially replaced by regenerative nodules and fibrotic tissue resulting in loss of liver function. "However, liver fibrosis, or even cirrhosis, was reported in PMM2-CDG, TMEM199-CDG, and NGLY1-CDDG." (PMID 34291020, 2021).
developmental disability (1 paper, 2020). Disorders in which there is a delay in development based on that expected for a given age level or stage of development. "Global developmental disability was observed in all reported cases and it may hardly be considered to be highly specific for NGLY1‐CDDG." (PMID 32071843, 2020).
GNE myopathy (1 paper, 2023). "This happened, for example, for acetazolamide (for PMM2-CDG, NCT04679389), oral GlcNAc Supplementation (for NGLY1 deficiency, NCT05402345), ManNAc (for GNE myopathy, NCT04231266), AVTX-803 (for Leukocyte Adhesion Deficiency type II, NCT05462587O)." (PMID 37644541, 2023).
hypolacrimia (1 paper, 2020). "Hyperkinetic movement disorder as well as alacrimia/hypolacrimia were observed in most patients and are thus rather specific for NGLY1‐CDDG." (PMID 32071843, 2020).
Infertility (1 paper, 2020). "When Ngly1−/− rats were reciprocally bred with Ngly1−/+ or Ngly1−/− rats, no female Ngly1−/+ or Ngly1−/− rat became pregnant, and there was no pup in these mating patterns, suggesting that Ngly1−/− causes infertility in rats." (PMID 32259258, 2020).
Kilquist syndrome (1 paper, 2020). An autosomal recessive multisystem disorder characterized by neurologic, gastrointestinal, and secretory dysfunction. "Strikingly, a recent clinical report describes a patient with a homozygous deletion in NKCC1 (null) who has many overlapping features with NGLY1 deficiency patients, including absence of saliva, tears, and sweat (Kilquist syndrome)." (PMID 33315011, 2020).
leukemia (1 paper, 2025). A malignant (clonal) hematologic disorder, involving hematopoietic stem cells and characterized by the presence of primitive or atypical myeloid or lymphoid cells in the bone marrow and the blood. "Furthermore, inhibition of NGLY1 by WRR139, a peptide vinyl sulfone, sensitizes leukemia cell lines to proteasome inhibition." (PMID 40643555, 2025).
liver cirrhosis (1 paper, 2020). "We also propose that NGLY1‐CDDG should be considered in patients presenting with unexplained liver cirrhosis." (PMID 32071843, 2020).
lysosomal storage disease (1 paper, 2020). A metabolic disorder caused by mutations in proteins critical for lysosomal function, including lysosomal enzymes, lysosomal integral membrane proteins, and proteins involved in the post-translational modification and trafficking of lysosomal proteins. "Together with the lysosomal storage diseases, NGLY1 deficiency is a congenital disorder of deglycosylation (NGLY1‐CDDG)." (PMID 32071843, 2020).
myelogenous leukemia (1 paper, 2020). "To learn more about NGLY1 deficiency in a human cell model, we edited the NGLY1 gene in a human myelogenous leukemia cell line, K562." (PMID 32265286, 2020).
myoclonus epilepsy (1 paper, 2020). "Here we report four patients with biallelic variants in NGLY1 who presented with myoclonus epilepsy, peripheral neuropathy, and metabolic markers suggestive for mitochondrial dysfunction." (PMID 31957011, 2020).
osteosarcoma (1 paper, 2019). A usually aggressive malignant bone-forming mesenchymal neoplasm, predominantly affecting adolescents and young adults. "In an attempt to winnow down the list of hits to at least one FDA-approved clinical candidate for NGLY1 deficiency, a total of 91 repurposing hits and novel suppressors from both worm and fly screens were cross-tested in a Keap1-NRF2 activation assay in the U2OS osteosarcoma cell line." (PMID 31615832, 2019).
respiratory infections (1 paper, 2023). "Some of the NGLY1 deficiency patients were reported to have recurrent, severe respiratory infections, while others were reported to have higher than expected antibody titers against rubella and rubeola after Measles, Mumps, and Rubella (MMR) vaccination." (PMID 37704604, 2023).
rheumatoid arthritis (1 paper, 2024). A chronic, systemic autoimmune disorder characterized by inflammation in the synovial membranes and articular surfaces. "Finally, we found through qRT-PCR experimental analysis that NDUFB3, NGLY1, and SLC25A4 are highly expressed in rheumatoid arthritis compared with normal tissues." (PMID 39421742, 2024).
yang deficiency (1 paper, 2022). Yang deficiency is a concept from traditional Chinese medicine. "The symptomatic gene targets for Yang deficiency (KAT2B, NFKB2, CREBBP, GTF2H3) or Yin deficiency (JUNB, JUND, NGLY1, TNF, RAF1, PPP1R15A) were potentially discovered." (PMID 35341155, 2022).